SIRT1 (sirtuin 1)
Diseases named in the same sentence as SIRT1 in open-access papers (continued):
Sharing a sentence is not in itself a finding about the gene and the disease.
tumor (continued). "These parameters define a metabolic–transcriptional rheostat that determines whether SIRT1 promotes oncogenic or tumor-suppressive outcomes in NSCLC." (PMID 41425553, 2025). "Furthermore, an in vivo murine subcutaneous tumor model was established to further confirm the role of Sirt1 in tumor progression." (PMID 40075208, 2025). "However, only Sirt1 overexpression significantly decreased DHT levels in the CSF of tumor-bearing mice." (PMID 40075208, 2025). "This overexpression correlates with increased tumor aggressiveness, suggesting that SIRT1 may serve as a prognostic biomarker in these subtypes." (PMID 41300302, 2025). "Additionally, both Sirt1 overexpression and finasteride reduced the levels of steroid enzyme in tumor tissue, with a more pronounced decrease observed in the Sirt1 overexpression group." (PMID 40075208, 2025). "We also found that SIRT1 plays a crucial role in the progression of tumor EMT and drug resistance." (PMID 40567502, 2025). "Furthermore, SIRT1-mediated hypoacetylation of H3K9 is associated with drug-resistant colony formation and the downregulation of tumor suppressors like SRFP1 and E-cadherin, resulting in the loss of an epithelial phenotype." (PMID 41300302, 2025). "Targeting SIRT1-mediated autophagy in liver CSCs could reduce tumor progression and impair drug resistance." (PMID 40052151, 2025). "These experiments indicated that SIRT1 in tumor cells could suppress anti‐tumor immunity through paracrine signaling." (PMID 39783838, 2025). "The cumulative effect of SIRT1 activation under CR is a coordinated cellular response that enhances DNA repair, reduces inflammation, improves mitochondrial function, and eliminates damaged cells, thereby creating a less favorable environment for tumor growth." (PMID 39940361, 2025). "However, a study analyzing 427 invasive ductal carcinoma cases found that higher SIRT1 expression in HER2+ tumors correlated with a lower risk of axillary lymph node metastasis (LNM), suggesting a potential tumor-suppressive role in this specific subtype." (PMID 41300302, 2025). "According to the literature data, SIRT1 expression in tumor cells varies." (PMID 40941911, 2025). "SIRT1 has a controversial point in the current study, we believe SIRT1 plays intricate roles in the tumorigenesis process, acting as both a tumor suppressor by inhibiting transcription to prevent tumor initiation and as a promoter of EMT, thereby inducing tumor metastasis and progression." (PMID 40229278, 2025). "In addition to its oncogenic activities, SIRT1 also has the potential to act as a tumor suppressor in specific contexts, particularly in regulating DNA repair and maintaining genomic stability." (PMID 41300302, 2025). "In luminal A, the level of expression of SIRT1 varied between different tumor grades (p < 0.001)." (PMID 39858444, 2025). "The results showed that the Sirt1‐KO group exhibited a significant decrease in the infiltration of immunosuppressive cells, such as M2‐type macrophages (Cd11b+Cd206+) and Treg cells (Cd4+Cd25+Cd127−), within the tumor tissue." (PMID 39783838, 2025). "However, the current methodology we employed involves establishing a subcutaneous tumor model in mice using cells with plasmid-mediated SIRT1 overexpression, followed by observation of subsequent tumor growth and mouse physiological/biochemical indicators." (PMID 40872615, 2025). "In contrast, SIRT1 activation promotes tumor growth and epithelial–mesenchymal transition (EMT)." (PMID 39940750, 2025).
tumor (continued). "Like CRC, SIRT1 can also regulate similar molecules that affect tumor progression in GC cells." (PMID 40567502, 2025). "While SIRT1 may support DNA repair and tumor suppression in early stages, it more commonly promotes tumor progression, metastasis, and therapy resistance in advanced disease." (PMID 41300302, 2025). "However, during carcinogenesis, SIRT 1 has both pro- and oncogenic effects, which provides a theoretical basis for SIRT1 as a target for tumor immunotherapy in combination with anti-ageing therapies." (PMID 40292294, 2025). "Furthermore, in orthotopic xenograft mouse model of HCC, SIRT1 knockdown reduced tumor incidence, and cambinol treatment significantly inhibited tumor growth of HCC94." (PMID 41281762, 2025). "The expression of SIRT1 is closely related to the drug resistance of various tumor cells." (PMID 41170449, 2025). "There are also studies where the tumor suppressor mechanism of SIRT1 is more complex." (PMID 40567502, 2025). "However, in subsequent years, the tumor-suppressive properties of SIRT1 were demonstrated, depending on the type of neoplasm." (PMID 40149343, 2025). "In this regard, we hypothesized that SIRT1 most probably has a tumor suppressor role or an oncogenic role in these subtypes." (PMID 39858444, 2025). "SIRT1 suppresses tumor growth by reducing inflammation and promoting oxidative metabolism, while SIRT6's role is controversial, linked to both oncogenic effects and tumor invasion." (PMID 40693828, 2025). "Nevertheless, SIRT1 was shown to have tumor suppressor function." (PMID 40283998, 2025). "Interestingly, we also observed that targeted inhibition of miR-155-5p/SIRT1 exhibited markedly reduced MDSC infiltration within the tumor microenvironment." (PMID 41281644, 2025). "However, SIRT1 can act either as a tumor suppressor or as an oncogene, depending on the cell context." (PMID 39935431, 2025). "However, contrasting findings suggest that SIRT1 can also act as a tumor suppressor by inhibiting β-catenin and NF-κB signaling pathways." (PMID 40567502, 2025). "Consequently, we propose that PI3K inhibition exerts its effect, at least in part, by suppressing the upstream recruitment of MDSCs, which are critical for upregulating the miR-155-5p/SIRT1 pathway in tumor cells." (PMID 41281644, 2025). "On one hand, tumor-intrinsic epigenetic factors such as SIRT1, CHD1, and MAP3K7 can determine whether a tumor is permissive or resistant to VSV infection, making them promising biomarkers for patient stratification." (PMID 41294689, 2025). "Furthermore, single-cell transcriptomic and redox profiling technologies have revealed significant heterogeneity in SIRT1 expression and redox adaptation among tumor-infiltrating immune cells, especially T-cells and myeloid populations." (PMID 41008982, 2025). "Additionally, our study suggests that Sirt1 acts as a tumor suppressor by promoting the deacetylation of FOXO1." (PMID 40075208, 2025). "Evidence suggests that SIRT1 may function as both a tumor suppressor and a tumor promoter, depending on the context." (PMID 40507674, 2025). "Increased H3K56Ac, resulting from hyperactive acetylation or improper SIRT1-mediated deacetylation, is associated with high tumor grade and dedifferentiation (though not proliferation)." (PMID 41300302, 2025). "In this context, SIRT1 is critical for chemoresistance and tumor progression." (PMID 41300302, 2025).
tumor (continued). "Sirt1 belongs to the protein deacetylase family and is involved in regulating glucose and lipid metabolism, inflammatory response, cell aging and apoptosis, oxidative stress, and tumor formation." (PMID 40291778, 2025). "Additionally, we found that the expression level of SIRT1 was negatively correlated with the apoptosis rate of tumor cells." (PMID 39783838, 2025). "Likewise, the alternative surrogates for SIRT1 inactivity showed clear trends to increase from stage II primary tumours to metastasis: AceH4 (P = 0.077) and Acep53 (K382) (P = 0.083)." (PMID 39494323, 2024). "Thus, SIRT1 assumes a multifaceted role in PCa, functioning simultaneously as a tumor promoter and a modulator of critical signaling pathways that contribute to disease progression." (PMID 39796040, 2024). "Nevertheless, the impact of Sirt1 on tumor necrosis in ccRCC remains unexplored." (PMID 38427808, 2024). "SIRT1 is a crucial ganglion-modulating protein involved in various physiological processes, such as aging, inflammation, oxidative stress, mitochondrial function protection, metabolic regulation, and tumor formation." (PMID 38044396, 2024). "In this study, we present an interesting mechanism wherein aspirin may impede SIRT1 activity by acetylating its functionally significant interior site, thereby triggering apoptosis in tumor cells." (PMID 38482749, 2024). "Capsaicin directly inhibits cellular tumor-associated nicotinamide adenine dinucleotide (NADH) oxidase (tNOX), leading to a concurrent decrease in silent mating type information regulation 2 homolog 1 (SIRT1) expression." (PMID 39371094, 2024). "Some studies suggest that SIRT1 may participate in maintaining the immunosuppressive tumor microenvironment by regulating the differentiation and function of MDSCs." (PMID 39845948, 2024). "Thus, the interaction between SIRT1 and autophagy plays a critical role in determining the responsiveness of tumor cells to chemotherapy." (PMID 39403142, 2024). "The SIRT1/leptin axis highlights the interplay between metabolic signaling and tumor progression." (PMID 39796040, 2024). "Resveratrol is a natural compound that activates SIRT1 and may help treat or prevent obesity, as well as tumor development, age-related decline in heart function, and loss of neurons." (PMID 38421832, 2024). "In addition, GAS5 is downregulated during CRC progression and functions as a competitive endogenous RNA for miR-34a,which is involved in the regulation of GAS5-inhibited tumor cell autophagy and triggers apoptosis via the mTOR/SIRT1 pathway." (PMID 39830506, 2024). "While tumor size differs between high- and low-expression groups for many HDAC members in many tumors, KIRC is the only one in which the expression of nine HDAC family members, HDAC1/5/8/10/11 and SIRT1/5/6/7, is associated with metastasis." (PMID 39063083, 2024). "Furthermore, it contributes to HCC by enhancing the stability of SIRT1 mRNA and inhibiting its degradation by miR-372, leading to increased SIRT1 expression and subsequent tumor growth." (PMID 38203767, 2024). "Notably, the use of SIRT1 inhibitors has been shown to significantly reverse its promoting effects on tumor progression." (PMID 39598398, 2024).
tumor (continued). "Furthermore, in an in vivo xenograft study employing tNOX-depleted melanoma cells, capsaicin therapy effectively suppressed tumor expansion by reducing tNOX and SIRT1 expression." (PMID 39371094, 2024). "Finally, the better therapeutic efficacy of 4-dmH was confirmed in tumor-bearing mice, which showed greater tNOX and SIRT1 downregulation and tumor volume reduction when treated with 4-dmH compared to heliomycin." (PMID 38567911, 2024). "Some researchers have found that Sirt1 upregulation could promote the stemness, metastasis, and radio-resistance of tumor cells by mediating protein deacetylation, and leading to protein nuclear-cytoplasmic translocation." (PMID 39080376, 2024). "Moreover, treatment of CRC cells with RSV suppressed their cross-talk with tumor microenvironment (TME) cells through activation of the Sirt1 pathway, thus abating cell survival and migration." (PMID 39220125, 2024). "Protein analysis of mouse tumor tissues further showed that 4-dmH exhibited greater inhibition of tNOX expression compared to heliomycin, but the two compounds were similar in their abilities to downregulate SIRT1 expression." (PMID 38567911, 2024). "In addition, programmed cell death induction is a novel finding in the use of SIRT1 to inhibit tumor progression." (PMID 39479446, 2024). "This difference in expression pattern suggests that SIRT1 may participate in tumor immune regulation through multiple mechanisms." (PMID 39845948, 2024). "Additionally, SIRT1 expression was correlated with tumor progression and prognosis in patients with CS." (PMID 36901967, 2023). "However, this contradictory role seems to depend on the cell type, the stage of tumor development, and the subcellular localization of SIRT1." (PMID 37627400, 2023). "Depletion of SIRT1 induced tumor cell arrest in the G0/1 phase." (PMID 36691046, 2023). "However, given the role of SIRT1 in tumor formation, caution must be taken when investigating therapeutic agents that activate the enzyme." (PMID 37456463, 2023). "The role of SIRT1 in tumor progression remains controversial." (PMID 37242510, 2023). "Additionally, astragalus polysaccharide has been found to inhibit tumor progression and lipid metabolism by regulating the miR-138-5p/SIRT1/SREBP1 pathway." (PMID 38189049, 2023). "Additionally, in one case of a dog with multi-cancer-like syndrome, downregulation of the SIRT1 gene expression was found, enhancing the notion of SIRT1 exhibiting a tumor protecting role." (PMID 37627400, 2023). "However, further studies are needed to elucidate SIRT1 pathways in canine mammary gland tumorigenesis, with the final goal to pharmacologically modulate its function, to either enhance its tumor-protecting role or suppress any tumor promoter function." (PMID 37627400, 2023). "Of these enzymes, SIRT1, the most investigated, may also be involved in cancerogenesis, although its possible dual role as an onco-suppressor and/or tumor promoter under a variety of biological conditions in humans and animals is still controversial." (PMID 37627400, 2023). "To further investigate the observed shifting SIRT1 expression from nuclear to cytoplasmic in tissue-derived tumor cells, we employed IF on homologue malignant canine cancer cell lines and noted that, in those malignant cell lines, SIRT1 expression was always cytoplasmic." (PMID 37627400, 2023). "We then explored whether SIRT1 augmented the ability of tumor cells to contend with stress conditions." (PMID 37063423, 2023).
tumor (continued). "Given the contradictory role that SIRT1 demonstrates with regard to tumorigenesis, caution must be taken when activating the enzyme for therapeutic purposes, as tumor formation instead of suppression could result." (PMID 37456463, 2023). "The controversial role of SIRT1 in tumorigenesis and tumor progression still remains open." (PMID 37627400, 2023). "Besides, the expression of signalling proteins p-β-catenin, β-catenin, AMPK and SIRT1 in each tumor were declined in both low and high dose groups in a different extent, compared to that of in solvent group." (PMID 36597133, 2023). "Discrepant SIRT1 level and activity may explain the controversial role of SIRT1 as tumor suppressor or tumor promoter in CRC." (PMID 37530744, 2023). "Thus, SIRT1 expression is a promising indicator of the conversion frequency of glucolipid metabolism and a predictor of tumor progression in CRC." (PMID 37063423, 2023). "Furthermore, several melatonin-related effects can be abolished via SIRT1 inhibition, indicating potential mediation by SIRT1 in non-tumor cells." (PMID 36851035, 2023). "SIRT1 can shuttle between the nucleus and the cytoplasm, and it seems that SIRT1 functions as a tumor suppressor or oncogene may depend on its subcellular localization." (PMID 37894746, 2023). "The regulatory functions of SIRT1 in different biological processes and molecular pathways are dependent on the type and stage of the neoplasia; thus, it may act as both an oncogenic and tumor suppressor factor and may also participate in drug resistance." (PMID 37833921, 2023). "Accordingly, some studies propose SIRT1 either as tumour suppressor or as tumor promoter in CRC." (PMID 37530744, 2023). "After tumor excision, SIRT1 and caspase 3 levels in tumor cells increased." (PMID 36901967, 2023). "However, in tumor cells, melatonin downregulates SIRT1, which results in proapoptotic and prooxidant activity." (PMID 36768253, 2023). "We speculated that the SIRT1 level is promising as a tumor progression biomarker and a therapeutic target." (PMID 37063423, 2023). "Because both IGF2BP2 and SIRT1 play an important role in tumor, we hypothesize that their mutual regulation also can affect the occurrence and development of ESCC, lncRNA HOXC‐AS1 acts as a molecular scaffold in this progress." (PMID 36510377, 2023). "The present results suggest that SIRT1 has dual roles as a tumor promoter and tumor suppressor." (PMID 38189049, 2023). "However, using SIRT1 level as a marker of malignancy is controversial since both increased or decreased SIRT1 tumour expression have been described in different studies, which points to a discrepancy between SIRT1 level and activity." (PMID 37530744, 2023). "Our results based on the clinical-pathological characteristics of patients with ccRCC showed that the expression of SIRT2, SIRT3, SIRT6, and SIRT7 was increased in tumor-stage 1-4 subgroups, SIRT1 was increased in tumor-stage 1, and the expression of SIRT4 and SIRT5was decreased." (PMID 37096064, 2023). "SIRT1 may target its nuclear substrates to exert its tumor suppressor function and target its cytoplasmic substrates to exert its tumor promoter function." (PMID 37627400, 2023). "Although it was also found that EGCG induces apoptosis in NPC cells through SIRT1 inhibition, however, whether SIRT1 acts as an oncogene or tumor suppressor may depend on the stages of tumor development or upstream and downstream regulators." (PMID 35548580, 2022). "In contrast, the tumor tissue of mCRC displayed the highest protein levels of SIRT1." (PMID 35205159, 2022).